HSF1 (heat shock transcription factor 1)
Diseases named in the same sentence as HSF1 in open-access papers (continued):
Sharing a sentence is not in itself a finding about the gene and the disease.
tumor (continued). "A recent study suggested dual inhibition of HSF1 and HSP90 for improved tumour reduction." (PMID 27563925, 2016). "Consistent with the upregulated protein level, HSF1 mRNA expression was also upregulated in tumor tissue compared with the paired non-tumor tissue as analyzed by real-time PCR." (PMID 26511079, 2015). "Although NVP-AUY922 activates HSF1, neither the MICA/B surface density on tumor cells nor their susceptibility to NK cell-mediated lysis was affected." (PMID 25854583, 2015). "Despite the HSF1 knockdown, tumor cell growth under standard cell culture conditions was not impaired." (PMID 25854583, 2015). "To investigate whether an inhibition of HSF1 can explain the effects of NZ28 on the NK cell-mediated cytotoxicity and MICA/B expression, we knocked down HSF1 in H1339 tumor cells by RNA interference." (PMID 25854583, 2015). "Multivariate analysis demonstrated a significant negative correlation between disease-free survival (DFS), overall survival (OS) and the HSF1 expression in stromal cells (P < 0.05) but not in tumor cells." (PMID 26511079, 2015). "HSP elevation in tumor cells can be induced by the highly malignant factor HRGβ1, which is a secreted factor that binds to c-erbB receptors and induces HSP expression through HSF1." (PMID 25147790, 2014). "HSF1 does not play a role of classical oncogene or tumor suppressor in carcinogenesis, but its activity influences many aspects of cell metabolism enabling tumor growth, which is summarized schematically in Fig.." (PMID 24467529, 2014). "HSF1 expression is significantly up-regulated in HCC, suggesting a tumor type that may be targeted by combinational treatment." (PMID 23615731, 2013). "However, HSF1 knockdown & NVP-HSP990 combination reduced the HSP90 inhibitor induced cell stress response and led to tumor stasis." (PMID 23615731, 2013). "Furthermore, in immortalized MEFs, HSF1 is essential for basal and EGF-induced migration, a process crucial for tumor invasion and metastasis." (PMID 24212658, 2011). "In case of HSF1-deprivation tumor cells die and tumors regress whereas normal cells do not depend on this protein." (PMID 22014102, 2011). "In a study on pancreatic tumorigenesis, HSF1 silencing led to the upregulation of pro-apoptotic proteins, including SMAC, cytochrome c, Apaf1, and cleaved caspase-3 and -9, suggesting that HSF1 inhibits the mitochondrial apoptosis pathway to promote tumor growth." (PMID 39850800, 2024). "HSF1 is crucial for processes such as G2 cell cycle arrest following radiation, the repair of double-stranded DNA breaks, the intrinsic promotion of EMT, and the upregulation of multidrug resistance 1 expression, which can extrude small molecule radiosensitizers from hypoxic tumor cells." (PMID 39655194, 2024). "TRPV1 blockade inhibits hyperthermia-induced calcium influx and subsequent nuclear translocation of HSF1, which selectively suppresses stressfully overexpressed HSP70 for enhancing thermotherapeutic efficacy against a variety of primary, metastatic and recurrent tumor models." (PMID 37120615, 2023). "To demonstrate that TRPV1 blockade might enable the manipulation of tumor stroma via suppressing HSF1-mediated TGFβ1 upregulation, we thus firstly investigated the influence of TRPV1 blockade on HSF1 distribution in the PANC02 tumor cells upon hyperthermia using immunofluorescence staining." (PMID 37120615, 2023). "Therefore, we examined alterations in HSF1 phosphorylation levels between primary tumor tissues and normal tissues." (PMID 34239690, 2021). "Thus, we reason that HSF1 is not directly involved in circadian-regulated HSP90 expression in our tumor models, particularly under nonstress conditions." (PMID 33579708, 2021). "Moreover, HSF1 induces noncanonical chaperone-independent tumor-promoting genes, together imparting a key co-oncogenic role on HSF1 in tumorigenesis." (PMID 34188043, 2021).
tumor (continued). "Moreover, we find HSF1 activated in tumor-infiltrating stroma of CAC patients and not in normal colon fibroblasts." (PMID 33288768, 2020). "Taking into consideration that both HSF1 and HSP90 are ones of the factors defining tumor growth and tumor resistance to therapeutics, such knowledge is crucial for a rational development that CDK5RAP3 may be examined as a potential target for anticancer therapy." (PMID 33182370, 2020). "The potent influence of HSF1 on metastasis may involve downstream effects on the tumor cells mediated through HSPs or may involve novel transcriptional targets for HSF1." (PMID 32331382, 2020). "As the HSF1 activation and subsequent induction of HSPs (including HSP40) can be provoked by hypoxia and/or low pH, an analogous HSF1/HSP40-dependent mechanism may act in hypoxic tumor regions, thereby contributing to EMT and the emergence of CSCs." (PMID 32268506, 2020). "Then, UBC modulated STAT5A and HSF1 in the WNT and the MAPK signaling pathways to inhibit DNA repair through the mediation of HIST2H2BE and to induce antiapoptosis through the mediation of HSPB1, which might finally facilitate tumor growth." (PMID 30344796, 2018). "Surprisingly there were no primary tumor sites with significant low-average rank (the lowest two are the thymus, p = 0.896, and the thyroid, p = 0.283), suggesting the absence of a strong suppression among HSF1-CanSig 8q genes in those primary tumor sites." (PMID 29268782, 2017). "Our dates revealed that only the high expression of HSF1 in stromal cells was related to poor prognosis, rather than the expression of HSF1 in nucleus in tumor cells, which demonstrated that the HSF1 activation in stromal cells was a key factor in the malignant elements." (PMID 26511079, 2015). "As HSF1 has been described to regulate the transcription of the NK cell ligands MICA and MICB, we investigated whether treatment of tumor cells with NZ28 and/or NVP-AUY922 alters the cell surface density [mean fluorescence intensity (MFI)] of the NK cell ligands MICA and MICB on tumor cells." (PMID 25854583, 2015). "The multivariate analysis demonstrated that except for certain conventional clinicopathological parameters, such as gender and nodal status, the HSF1 in stromal cells but not in tumor cells was an independent unfavorable factor for DFS (P = 0.019) and OS (P = 0.017)." (PMID 26511079, 2015). "Furthermore, multivariate Cox model analysis showed that only HSF1 expression in stromal cells but not in tumor cells was an independent prognostic marker for ESCC." (PMID 26511079, 2015). "To determine whether KIF14 overexpression in OvCa tumors could also be linked to transcriptional regulation, we measured mRNA expression of Sp1, YY1 and HSF1 in a subset of OvCa tumor tissues with (15 samples) and without (50 samples) KIF14 genomic gain." (PMID 24626475, 2014). "Based on the clinical diagnosis [using the tumor, nodes and metastasis grading system], 44.0% of phase I-II HCC tissues (n=11/25) demonstrated low levels of HSF1 protein expression, which was significantly different to the 83.3% of phase III and IV HCC tissues that exhibited high HSF1 expression." (PMID 25199534, 2014). "HSF1 by itself does not act as a classical oncogene or tumor suppressor." (PMID 24212658, 2011). "Therefore, the interplay between HSF1 and HSF2 may regulate their function and play an important role on tumor progression by activating target genes." (PMID 20537126, 2010). "Our analysis across tumor types showed that MYC amplification occurred without amplification of HSF1 in a lower percentage of patients, whereas HSF1 was also amplified without MYC amplification." (PMID 39831777, 2025). "An example of the efficacy of the hyperactivation of ERK in tumor cells is demonstrated by the compound ACA-28, although data regarding its impact, or that of similar compounds, on HSF1 activity is currently lacking in the literature." (PMID 39682216, 2024).
tumor (continued). "HSF1 activity is amplified in many tumor contexts in a manner that resembles a chronic state of stress, characterized by high levels of HSP gene expression as well as HSF1-mediated non-HSP gene regulation." (PMID 32331382, 2020). "The results showed that, regardless of the chip or protein levels, VPS28, HSF1, and PUF60 showed higher expression in tumour tissues than in normal tissues, while COL17A1 and SMOC1 showed significantly higher expression in the adjacent tissues compared with the tumour tissues." (PMID 32964046, 2020). "A knockdown of HSF1 decreases the membrane expression of MICB but not that of MICA, whereas a treatment with NZ28 inhibits the expression of both, MICA and MICB on the surface of the investigated tumor cells." (PMID 25854583, 2015). "Unlike HSF1, the role of HSF2 in tumor progression is unclear." (PMID 20537126, 2010).
neurodegenerative disease (39 papers, 2010 to 2026). A disorder of the central nervous system characterized by gradual and progressive loss of neural tissue and neurologic function. "Pharmacological approaches for maintaining or enhancing proteostasis and cytoskeletal integrity by rescuing hsf-1 deficiency are promising and potential strategies for extending lifespan and neurodegenerative disease interventions." (PMID 35096951, 2021). "It has been reported that hsf-1 deficiency with aging is associated with neurodegenerative diseases." (PMID 35096951, 2021). "Activation of the HSF1 pathway has been proposed to be protective in several neurodegenerative diseases associated with protein aggregation as a means to combat the cellular effects of toxic proteins." (PMID 29973287, 2018). "A number of studies have linked loss of either HSF1 or autophagy to the promotion of neurodegenerative diseases." (PMID 29036198, 2017). "Pharmacological enhancement of HSF1 activity could offer therapeutic and preventive benefits for individuals at risk of or suffering from neurodegenerative diseases." (PMID 40287736, 2025). "Meanwhile, multiple reports have shown that the HSF1 activation suppresses protein aggregation that causes neurodegenerative diseases, suggesting the possibility that the HSF1 activation caused by RSS is involved in the suppression of neurodegenerative diseases." (PMID 37060999, 2023). "Thus, LBE may be a potential therapeutic agent for neurodegenerative diseases characterized by hsf-1 deficiency." (PMID 35096951, 2021). "Given that HSF1 coordinately activates the expression of multiple protein chaperones and other cytoprotective genes, HSF1 activation could be of potential therapeutic value in neurodegenerative diseases associated with a wide array of manifestations of protein misfolding." (PMID 20098725, 2010). "Another study indicates that HSF1 responds to pathological proteins in neurodegenerative diseases by increasing heat shock protein expression." (PMID 39754217, 2025). "On the contrary, drugs that promote HSF1 activity are also being evaluated as potential treatments, namely in the context of neurodegenerative diseases, such as Alzheimer's, Parkinson's disease, and amyotrophic lateral sclerosis." (PMID 35485710, 2022). "In order to use HSF1 activation as a treatment for neurodegenerative diseases, the transcription factor has to be activated very specifically, without causing further cell stress or damage." (PMID 35218516, 2022). "The impairment of HSF1 activity or its depletion exacerbates protein misfolding and aggregation, and decreases chaperone HSPs expression, thereby contributing to neurodegenerative diseases progression." (PMID 35656110, 2022). "It will be important to examine transcriptional changes in HSF1 in post-mortem brain samples of additional neurodegenerative diseases." (PMID 29973287, 2018). "Pharmacological activation of HSF1 has been proposed as a therapeutic strategy to enhance protein chaperone function and neuronal survival in neurodegenerative disease." (PMID 29973287, 2018). "Small molecule activators of HSF1 have now been identified and shown to have neuroprotective effects in cell or animal models of neurodegenerative diseases." (PMID 28293421, 2017). "Inhibition of Hsp90 releases HSF-1 from the Hsp90 complex resulting in subsequent production of Hsps, and induction of Hsp70 by Hsp90 inhibitors is well documented in neurodegenerative disease models." (PMID 20525284, 2010). "Studies are currently under way to address these issues and further explore HSF1's potential as a therapeutic target in protein misfolding–related neurodegenerative diseases." (PMID 20087417, 2010). "Our work suggests that stress-induced transcription factor condensates drive conserved responses during physiological perturbations, but can be inactivated during pathological insults, rationalizing HSF1 and transcriptional dysfunction across degenerative diseases and toxic exposures." (PMID 41727155, 2026).
neurodegenerative disease (continued). "While HSF1 activity offers neuroprotective benefits in neurodegenerative diseases, its proteome-stabilizing function may also reinforce tumorigenic transformation." (PMID 40287736, 2025). "While impaired HSF1 activation does not directly cause neurodegenerative diseases, it contributes to plaque formation, neuronal cell death, and disease progression due to increased protein misfolding and aggregation." (PMID 40287736, 2025). "Impairment of hsf-1 activity or expression in neurodegenerative diseases has been widely confirmed." (PMID 35096951, 2021). "GSEA results of KEGG analysis indicated that HSF1 was involved in various pathways, such as the spliceosome, ribosome biogenesis, Vibrio cholera infection, oxidative phosphorylation, mitophagy, thermogenesis, and neurodegenerative diseases." (PMID 34239690, 2021). "Understanding of these novel mechanisms by which HSF1 protects neurons could lead to the development of therapeutic approaches for neurodegenerative diseases." (PMID 30467350, 2018). "For instance, impairment of HSF1-mediated stress response, reflected by failed induction of chaperone proteins to neuronal stresses can significantly impact the onset, development, and progression of stress-related neurodegenerative diseases." (PMID 26503960, 2016). "By contrast, a lack of Hsf1 activity has been suggested to contribute to neurodegenerative diseases with hallmark protein aggregates, and activation of Hsf1 has been proposed as a therapeutic avenue." (PMID 27831465, 2016). "A number of reports suggest that HSP90 may be a viable target for neuroprotection, as HSP90 inhibitors have been found to promote HSF1 release and augment the heat-shock response, which protects against neurotoxic insults in a variety of models of neurodegenerative disease." (PMID 34073043, 2021). "Agents targeting HSF1 or other master regulators of the proteostatic network have the advantages of being fast-acting and relatively agnostic to the identities of the misfolded proteins involved in a given neurodegenerative disease and to their mechanisms of aggregation and toxicity." (PMID 28293421, 2017). "Although the precise mechanisms underlying this defect in HSF1 activation are not clear, this could, in part, explain the selective sensitivity of neuronal cells in neurodegenerative diseases in which misfolded proteins are expressed in all tissues." (PMID 20098725, 2010). "Most neurodegenerative diseases are “protein misfolding disorders” that could therapeutically benefit from active small molecules that regulate HSF1 or modulate chaperone activities that could possibly ameliorate the prevailing imbalance in protein homeostasis." (PMID 20938400, 2010). "It is known that the expression of sHSP is primarily determined by the transcription factor HSF-1, while decreased activity of HSF-1 has been shown to be a key part of the deleterious cascade in neurodegenerative disease." (PMID 34567416, 2021). "In addition, this ability to functionally activate HSF1 in mammalian neurons and human cells, in the absence of proteotoxicity, through activation of 5HT4 receptors could have implications for the treatment of neurodegenerative diseases where HSF1 is protective." (PMID 32324136, 2020). "Since the induction of HSPs is primarily determined by the activation of heat shock transcription factor 1 (HSF1), HSF1 has been regarded as an attractive target for treating neurodegenerative diseases." (PMID 26503960, 2016). "Indeed, HSF1, partly through the induction of chaperones that inhibit protein aggregation like HSP27, displays a protective effect against neurodegenerative diseases." (PMID 24212658, 2011). "Our study may provide the first evidence of increased, rather than impaired, activity of HSF1 based on human brain samples for a specific neurodegenerative disease." (PMID 29973287, 2018).
neurodegenerative disease (continued). "Therefore, screening for compounds that disrupt the HSP90:HSF1 interaction, but do not inhibit HSP90 function, would provide potential candidates for developing neurodegenerative disease treatment." (PMID 40239269, 2025).